CT62 (cancer/testis associated 62)
Gene: Long non-coding RNA gene on chromosome 15 (71,110,244 to 71,116,593, reverse strand). Ensembl gene ENSG00000225362.
Diseases named in the same sentence as CT62 in open-access papers:
CT62 is named in the same sentence as 5 diseases in open-access papers, as found by Europe PMC text mining. Sharing a sentence is not in itself a finding about the gene and the disease. The quoted sentences say what the papers report.
glioma (1 paper, 2022). A benign or malignant brain and spinal cord tumor that arises from glial cells (astrocytes, oligodendrocytes, ependymal cells). "Considering that immune cells are an important component of the tumour environment, glioma‐derived exosomes would deliver CT62, DPY19L2P1, and KCNH1‐IT1 to immune cells, regulating the tumour immune microenvironment." (PMID 35194922, 2022). "Considering that immune cells are an important component of the tumor environment, glioma‐derived exosomes would deliver CT62, DPY19L2P1 and KCNH1‐IT1 to immune cells, regulating the tumour immune microenvironment." (PMID 35194922, 2022).
malignant glioma (1 paper, 2022). A grade III or grade IV glioma arising from the central nervous system. "Therefore, the low expression of CT62, DPY19L2P1, KCNH1‐IT1 and VPS33B in malignant glioma would promote the formation of M2 macrophages and thus promote malignant glioma tumorigenesis and progression." (PMID 35194922, 2022). "Fourteen genes within the tumour immune microenvironment pathway (AC020907.1, Y_RNA, TMEM72‐AS1, KRT16P2, DLX6‐AS1, AP002414.1, hsa‐miR‐424, TBPL1, NPAS2, CRY2, VPS33B, CT62, DPY19L2P1, and KCNH1‐IT1) were used to construct a model to evaluate the importance of these genes in malignant glioma." (PMID 35194922, 2022).
Sepsis (1 paper, 2023). Sepsis is defined as life-threatening organ dysfunction caused by a dysregulated host response to infection. "Gene entities exhibiting stronger expression in the SIRS-ranked dataset included CFC1, CT62, lnc-DAAM2-1 and lnc-LTBP3-2 and in the sepsis-ranked dataset included TDRD9, DAAM2, OLFM4 and OLAH." (PMID 38332914, 2023).
cancer (1 paper, 2023). A tumor composed of atypical neoplastic, often pleomorphic cells that invade other tissues. "According to our study, in HCC, we extracted RCORs-miRNA-lncRNA pairs, such as RCOR1-hsa-miR-9-3p-CT62, RCOR2-hsa-miR-1343-3p-LINC02693, RCOR3-hsa-miR-128-3p, etc., offering potential targets for cancer therapy." (PMID 37342230, 2023).
tumor (1 paper, 2022). "Therefore, VPS33B would promote exosomes carrying CT62, DPY19L2P1 and KCNH1‐IT1 to other cells, thus regulating the tumor microenvironment." (PMID 35194922, 2022). "Therefore, VPS33B would promote exosomes carrying CT62, DPY19L2P1, and KCNH1‐IT1 to other cells, thus regulating the tumour microenvironment." (PMID 35194922, 2022).